ASF1A (anti-silencing function 1A histone chaperone)
Description:
Histone chaperone that facilitates histone deposition and histone exchange and removal during nucleosome assembly and disassembly. Cooperates with chromatin assembly factor 1 (CAF-1) to promote replication-dependent chromatin assembly and with HIRA to promote replication-independent chromatin assembly. Promotes homologous recombination-mediated repair of double-strand breaks (DSBs) at stalled or collapsed replication forks: acts by mediating histone replacement at DSBs, leading to recruitment of the MMS22L-TONSL complex and subsequent loading of RAD51. Also involved in the nuclear import of the histone H3-H4 dimer together with importin-4 (IPO4): specifically recognizes and binds newly synthesized histones with the monomethylation of H3 'Lys-9' and acetylation at 'Lys-14' (H3K9me1K14ac) marks, and diacetylation at 'Lys-5' and 'Lys-12' of H4 (H4K5K12ac) marks in the cytosol. Required for the formation of senescence-associated heterochromatin foci (SAHF) and efficient senescence-associated cell cycle exit.
Synonyms: CIA; CGI-98; HSPC146; DKFZP547E2110
Tractability: Small molecule: a high-quality ligand is known. PROTAC: ubiquitination databases record sites on it; its protein half-life has been measured; a small molecule that binds it is known.
Target class: Other nuclear protein
Gene: Protein-coding gene on chromosome 6 (118,894,152 to 118,909,171, forward strand). Ensembl gene ENSG00000111875.
Subcellular location: Nucleus; Chromosome
Subcellular location (Human Protein Atlas): Nucleoplasm
Pathways (Reactome):
Cellular responses to stimuli: Formation of Senescence-Associated Heterochromatin Foci (SAHF)
Gene Ontology:
Molecular function: histone binding; histone chaperone activity; protein binding; chromatin binding
Biological process: DNA repair; DNA repair-dependent chromatin remodeling; DNA replication-dependent chromatin assembly; nucleosome assembly; replication fork processing; transcription elongation-coupled chromatin remodeling; protein import into nucleus; chromatin organization
Cellular component: chromatin; chromosome; nucleoplasm; nucleus; protein-containing complex; site of double-strand break; histone acetyltransferase complex
Genetic constraint (gnomAD): Loss-of-function variants: 4 observed, 16.03 expected, observed/expected ratio (o/e) 0.25, 90% interval 0.12 to 0.57. The upper end of that interval is the gene's LOEUF score, 0.57, which puts it in group 2 of 6, group 1 being the genes least tolerant of losing a copy. Missense variants: 116 observed, 208.36 expected, observed/expected ratio (o/e) 0.56, 90% interval 0.48 to 0.65. Synonymous variants: 86 observed, 78.72 expected, observed/expected ratio (o/e) 1.09, 90% interval 0.92 to 1.31.
Homologues: Orthologues: chimpanzee ASF1A (100% identical), dog ASF1A (100% identical), macaque ASF1A (100% identical), mouse Asf1a (99% identical), pig ASF1A (99% identical), tropical clawed frog asf1a (92% identical), guinea pig ASF1A (87% identical), rat Asf1a (87% identical), rabbit ASF1A (82% identical), Drosophila melanogaster asf1 (60% identical), Caenorhabditis elegans unc-85 (43% identical), Caenorhabditis elegans asfl-1 (43% identical). Paralogues in human: ASF1B (71% identical).
Diseases named in the same sentence as ASF1A in open-access papers:
ASF1A is named in the same sentence as 23 diseases in open-access papers, as found by Europe PMC text mining. Sharing a sentence is not in itself a finding about the gene and the disease. The quoted sentences say what the papers report.
breast carcinoma (5 papers, 2018 to 2025). "Our findings suggest that inhibition of the enzymatic activity of USP52 or disruption of the association of USP52 with ASF1A, combined with chemo- or radio-therapy, could potentially improve the treatment of breast cancer." (PMID 29599486, 2018). "Analysis of breast cancer cell viability showed that the USP52/ASF1A signaling promotes tumor cells resistance to ionizing radiation." (PMID 34575114, 2021). "Quantitation analysis of the stainings showed that the expression levels of USP52 and ASF1A were highly expressed in various types of breast carcinoma samples, and the levels of their expression strongly correlated with each other." (PMID 29599486, 2018). "Since complicated heterogeneity observed in breast cancer, it will, however, be important to determine to what extent USP52 and/or ASF1A affect tumor survival across genetically distinct subgroups of breast cancer." (PMID 29599486, 2018). "Collectively, these results support the notion that USP52-promoted ASF1A stabilization confers cellular resistance of breast cancer cells to genotoxic insults." (PMID 29599486, 2018). "Moreover, we reveal that impairment of USP52-promoted ASF1A stabilization results in growth arrest of breast cancer cells and sensitizes these cells to DNA damage." (PMID 29599486, 2018). "In this study, we revealed that the expression level of USP52 and ASF1A is upregulated in breast cancer and positively correlates with each other, and, indeed, USP52-promoted ASF1A stabilization is required for breast cancer cells to combat with genotoxic insults." (PMID 29599486, 2018). "Additionally, we find that USP52 is overexpressed in breast carcinomas, and its level of expression correlates with that of ASF1A." (PMID 29599486, 2018). "Next, we demonstrated USP52 deficiency rendered breast cancer cells hypersensitive to camptothecin (CPT), a type of DNA damaging agent impairing replication fork progression, while cells stably expressing ASF1A overcome the effect induced by USP52 depletion." (PMID 29599486, 2018). "In breast cancer, USP52 has been shown to decrease the ubiquitination level of the histone chaperone ASF1A, thereby stabilizing its protein and promoting cell proliferation as well as enhancing DNA damage tolerance." (PMID 40962058, 2025). "In summary, the ATM/ZEB1/USP7/CHK1, miR-200c/LINC02582/USP7/CHK1, USP7/PHF8, UCHL3/RAD51, USP52/ASF1A, and UCHL1/HIF-1 signaling axis are potential targets to improve the radiosensitivity of breast cancer." (PMID 34575114, 2021). "We reveal that USP52 promotes chromatin assembly through stabilizing ASF1A, and point a role of USP52 in breast carcinogenesis and cellular resistance of breast cancer cells to DNA damage." (PMID 29599486, 2018). "It has been reported that ASF1B, rather than ASF1A, is critical for proliferation and has highly significant prognostic value in breast cancer and cervical cancer." (PMID 35360875, 2022). "The TCGA dataset analysis revealed a negative correlation between ASF1a and p21cip1 expression in multiple types of primary tumors, including HCC, prostate, gastric, and breast cancer." (PMID 30692519, 2019). "The TCGA data revealed a negative correlation between ASF1a and p21cip1 expression in HCC, prostate cancer (PCa), gastric cancer (GC), and breast cancer (BC)." (PMID 30692519, 2019).
lung carcinoma (4 papers, 2015 to 2023). "We found that both RAD6A and RAD6B showed downregulated expressional levels in human lung cancers compared with normal lung tissues, while the expression of both ASF1A and ASF1B are upregulated." (PMID 26336826, 2015). "Collectively, loss of SETD2-mediated H3K36me3 is associated with increased chromatin recruitment of histone chaperones ASF1A/B, enhanced histone exchange, and increased H3K56ac deposition in both kidney and lung cancers, all of which is analogous to the findings observed in Set2-deficient yeast." (PMID 36810256, 2023). "Human lung cancer cell line H1299 cells were transfected an GFP empty vector, or an GFP-tagged RAD6A plasmid, or a Red-tagged ASF1A plasmid, or RAD6A and ASF1A plasmids together." (PMID 26336826, 2015).
hepatocellular carcinoma (3 papers, 2015 to 2024). A malignant tumor that arises from hepatocytes. "We first investigated the correlation between RAD6 and MDM2 protein levels and ASF1A and H3K56Ac levels in the normal liver cell line HL-7702 and in different hepatoma cell lines (SMMC, HepG2, Hep3B and Huh7)." (PMID 26336826, 2015). "The results indicated that ASF1A protein levels and H3K56Ac levels were increased in hepatoma cell lines, while RAD6 protein levels were decreased in hepatoma cell lines (upper)." (PMID 26336826, 2015). "Elevated ASF1a mRNA expression was observed in hepatocellular carcinoma (HCC) tumors." (PMID 30692519, 2019). "We used a normal hepatocyte-derived cell line (LO2) as the control and compared the relative expression levels of ASF1A and HJURP in LO2 and five hepatocellular carcinoma (HCC) cell lines (Hep3B, Huh-7, LM3, SNU-368, SNU-739) using qRT‒PCR) and WB experiments." (PMID 38561384, 2024). "However, the decrease of RAD6 protein levels likely determined the upregulation of ASF1A and H3K56Ac levels although MDM2 levels were increased in hepatoma cell lines." (PMID 26336826, 2015).
lung adenocarcinoma (3 papers, 2022 to 2024). A carcinoma that arises from the lung and is characterized by the presence of malignant glandular epithelial cells. "In lung adenocarcinomas, ASF1A deficiency could sensitize lung adenocarcinomas to anti-PD-1 therapy by inducing immunogenic M1-like macrophage differentiation and enhancing T cell activation of the TME." (PMID 36755810, 2023). "Recently, ASF1A has been reported to inhibit the sensitization of Kras-mutant lung adenocarcinoma to anti-PD-1 treatment." (PMID 36184659, 2022).
acute kidney injury (2 papers, 2023). Sudden and sustained deterioration of the kidney function characterized by decreased glomerular filtration rate, increased serum creatinine or oliguria. "Another study found that LncRNA XIST competitively binds hsa-miR-212-3p to regulate the expression of ASF1A in acute kidney injury." (PMID 37280692, 2023).
breast tumor (1 paper, 2018). "To further establish the role of USP52/ASF1A in cancer cell proliferation and breast carcinogenesis, we transplanted two types of breast tumor, developed from MCF-7 cells infected with control lentivirus or lentivirus carrying USP52 shRNAs, onto the mammary fat pads of athymic mice." (PMID 29599486, 2018).
diffuse large B-cell lymphoma (1 paper, 2023). "For example, ASF1A is deleted in 10% of diffuse large B-cell lymphoma TCGA samples, making ASF1B a possible target." (PMID 36707513, 2023).
leukemia (1 paper, 2022). A malignant (clonal) hematologic disorder, involving hematopoietic stem cells and characterized by the presence of primitive or atypical myeloid or lymphoid cells in the bone marrow and the blood. "Our results show that ASF1A is aberrantly upregulated in bone marrow samples from patients with CML-BC compared to newly diagnosed CML-CP, and ASF1A inhibits differentiation of leukemia cells into granulocytes and macrophages, thereby driving the transformation to CML-BC." (PMID 36184659, 2022).
ovarian carcinoma (1 paper, 2015). A malignant neoplasm originating from the surface ovarian epithelium. "Besides, similar results were also obtained in ovarian cancer patients (data not shown) indicated that the negative correlation between RAD6 and ASF1A is possibly a general event occurred in tumorigenesis." (PMID 26336826, 2015).
prostate carcinoma (1 paper, 2019). A carcinoma that arises from epithelial cells of the prostate gland.
viral infection (1 paper, 2018). "While the histone chaperones HIRA and ASF1A have been implicated in the initial loading of histones onto HSV DNA during the first few hours of infection, these reports also demonstrated that HIRA and ASF1A actually promote productive viral infection." (PMID 30465651, 2018).
tumor (19 papers, 2012 to 2025). "In KRAS-mutated tumor cells, the mechanistic study indicates that endogenous anti-silencing function protein 1 homolog A (Asf1a) deficiency induces polarization of M1-like macrophages by upregulating GM-CSF expression." (PMID 39144141, 2024). "Loss of ASF1A sensitized tumor cells to anti-PD-1 treatment by promoting M1-like macrophage polarization and T-cell activation." (PMID 35372044, 2022). "ASF1A loss, combined with anti-PD-1 antibodies, exerts a significant tumor growth inhibition in K-Ras LUAD models." (PMID 32516941, 2020). "Tumor cell-intrinsic Asf1a deficiency promotes inflammation and M1-like macrophages via secretion of GM-CSF, with T-cell activation." (PMID 32516941, 2020). "Additionally, intrinsic Anti-Silencing Function 1A Histone Chaperone (ASF1A) deficiency in tumor cells can enhance anti-PD-1 therapy efficacy by upregulating Granulocyte–Macrophage Colony-Stimulating Factor (GM-CSF) expression." (PMID 39538305, 2024). "Additionally, intrinsic ASF1A deficiency in tumor cells can enhance anti-PD-1 therapy efficacy by upregulating GM-CSF expression." (PMID 39538305, 2024). "ASF1A knockdown reduced H3K56ac in vivo by a xenograft tumor model, suggesting that ASF1A enhanced the development of CML via H3K56ac in vivo." (PMID 36184659, 2022). "To investigate the physiological and pathological relevance of ASF1A in the development of CML in vivo, we established a xenograft tumor model by injecting K562 cells transduced with shRNA against ASF1A (or scrambled shRNA) subcutaneously into NOD-SCID mice." (PMID 36184659, 2022). "Recent studies uncover Asf1a as a tumor-intrinsic suppressor of immune checkpoint blockade through suppression of GM-CSF expression." (PMID 33691643, 2021). "Collectively, these results point a role of the USP52-promoted ASF1A stabilization in promoting breast carcinogenesis." (PMID 29599486, 2018). "Moreover, immunohistochemistry (IHC) of serial sections from HCC patients proved the elevated expression of ASF1A and HJURP in tumor tissues, and HCC patients in the high-risk group had poorer prognosis by IHC staining of HCC tissue microarrays." (PMID 38561384, 2024). "Furthermore, we observed that the tumors derived from ASF1A knockdown group were much smaller, and the tumor size and weight were reduced in the ASF1A knockdown groups." (PMID 36184659, 2022). "To test this hypothesis, we first analyzed the protein expression levels of USP52 and ASF1A with human tissue arrays including series of tumor samples with each type of cancer having three malignant samples paired with adjacent normal tissues." (PMID 29599486, 2018). "We therefore questioned whether RAD6-MDM2-regulated ASF1A degradation participates in tumor development." (PMID 26336826, 2015). "Therefore, understanding how the abundance of ASF1A is regulated in physiological state and how it is dysregulated in malignancies is of great importance to the understanding of genome/epigenome integrity and tumor development, respectively." (PMID 29599486, 2018). "Immunohistochemical (IHC) staining showed that ASF1A and HJURP were expressed more highly in tumor tissues than in normal tissues." (PMID 38561384, 2024). "Intriguingly, the RNA levels of ASF1A and HJURP also gradually increased with tumor stage progression in the TCGA-LIHC data." (PMID 38561384, 2024). "Statistical analysis showed increasing mean densities of ASF1A and HJURP with tumor development and progression." (PMID 38561384, 2024). "IHC analysis of multiple tumor and adjacent tissues revealed that the expression levels of USP52 and ASF1A are both upregulated in breast and rectum tumors." (PMID 29599486, 2018).
tumor (continued). "We found that RAD6 protein levels decreased mostly in the cancer samples compared with the pericarcinous tissue, while the ASF1A, H3K56Ac and MDM2 levels increased significantly in most of the tumor samples." (PMID 26336826, 2015). "ASF1a protein expression in collected tumor samples was also higher than that in the non-tumorous samples." (PMID 30692519, 2019). "Furthermore, ASF1B levels, but not ASF1A levels, have a highly significant positive correlation with tumor size, tumor grade, and mitotic cell number." (PMID 35360875, 2022). "ASF1A, not ASF1B, regulates histone H3K56Ac levels and is increased in many tumor tissue types together with H3K56Ac levels." (PMID 26336826, 2015). "We found that overexpression of RAD6A inhibits the cell proliferation, while overexpression of ASF1A promotes the proliferation of H1299 cells, suggesting an negative effect of RAD6 and ASF1A in tumor cell proliferation." (PMID 26336826, 2015).